INS (insulin)
Diseases named in the same sentence as INS in open-access papers (continued):
Sharing a sentence is not in itself a finding about the gene and the disease.
Insulin resistance (continued). "Therefore, insulin resistance is often accompanied by hyperglycemia and hyperinsulinemia, until β-cells cannot maintain a compensatory increase in insulin, eventually leading to T2D." (PMID 36230963, 2022). "Our data reveal that LLPS-derived IRS1 condensates may function as intracellular signal hubs to execute insulin signal transduction and that impaired formation of IRS1 condensates is associated with insulin resistance." (PMID 35790738, 2022). "Strikingly, treatment with EA for only 2 weeks reduced the obesity-elevated leptin and insulin levels by 69.3% and 58.5%, respectively, in obese mice, which is likely due to improved obesity and insulin resistance consistent with previous findings in this mouse model." (PMID 36386896, 2022). "Similar to previous studies, the type 2 diabetes PRS was associated in our study with indices suggesting deficient insulin secretion but not with insulin resistance." (PMID 35501401, 2022). "Defective central insulin signaling secondary to obesity‐related peripheral insulin resistance may induce tau phosphorylation via activation of GSK‐3β." (PMID 35662390, 2022). "In addition to its previous similarities with metabolic syndrome, obesity often leads to a permanent form of insulin resistance in peripheral tissues, disrupting the insulin signaling used in this process of host defense." (PMID 35711466, 2022). "Insulin resistance was induced in zebrafish by immersion in insulin solution at 72 and 96 hpf." (PMID 35955446, 2022). "Therefore, the elevation of insulin levels in MetS precedes other metabolic disorders and MetS arises from insulin resistance." (PMID 36419559, 2022). "Myostatin positively correlated with insulin resistance (fasting insulin levels and HOMA-IR)." (PMID 35631274, 2022). "It presented significantly increased serum gremlin levels in the affected individuals, in comparison to the controls, and positive correlations with various markers of insulin resistance, such as insulin levels, HOMA-IR and waist-to-hip ratio (WHR) were observed." (PMID 35206286, 2022). "Additionally, they reported a marked reduction in fasting insulin, insulin resistance, and oxidative stress." (PMID 35276815, 2022). "In addition, we detected that CSNO significantly activated the insulin signaling pathway under insulin resistance." (PMID 36313766, 2022). "Insulin resistance is defined as a profound dysregulation of the insulin signaling system and represents a state of the impaired ability of peripheral tissues to respond to the physiological levels of insulin." (PMID 35190737, 2022). "In summary, SA could activate the PI3K/AKT/GLUT2 protein pathway, regulate glucose metabolism gene expression, enhance insulin sensitivity, and improve insulin resistance." (PMID 36618687, 2022). "As insulin suppresses Hmgcs2 expression in hepatocytes, it is reasonable to postulate that higher insulin levels inhibit ketogenesis in the presence of hepatic insulin resistance." (PMID 35421611, 2022). "Short-term vitamin D administration could improve insulin, glucose, and insulin resistance in NAFLD patients consequently improving the liver enzymes." (PMID 35927637, 2022). "We speculate that the temporary insulin resistance observed during refeeding is consistent with prior reports of fasting-induced insulin resistance during the metabolic switch from ketones to glucose." (PMID 36296997, 2022). "Concordantly, our data favor the hypothesis that once insulin resistance is installed, insulin production will increase and can progress to β-cell failure over time." (PMID 35360053, 2022). "Oxidative stress disrupts normal insulin signaling and progressively induces insulin resistance." (PMID 36590224, 2022). "As is well-known, obesity causes adipocyte proliferation, and hypertrophy, as well as an increase in the metabolism of adipocytes, thereby reducing the insulin sensitivity of skeletal muscle and producing insulin resistance, and thus, inducing type two diabetes." (PMID 36297031, 2022).
Insulin resistance (continued). "Insulin resistance, in short, is that insulin cannot function normally." (PMID 35574038, 2022). "Our findings of an inverse association between vitamin D status and fasting glycemia and the null association with HOMA-IR suggest an effect via insulin secretion rather than insulin resistance." (PMID 35906229, 2022). "In addition, heat-stress increases beta-cell dysfunction and insulin resistance; and reduces glucose uptake by insulin target tissues, leading to GDM." (PMID 35162797, 2022). "In the obese state, macrophages infiltrate the target organ, are activated to the M1 polarization state and produce abundant inflammatory cytokines, which negatively affect the transmission of insulin signals and increase the development of chronic inflammation, as well as insulin resistance." (PMID 36230963, 2022). "There is also a significant positive association between serum ferritin with insulin, insulin resistance, serum cholesterol, LDL, and triglycerides, and a negative association with serum HDL (p-value < 0.001)." (PMID 35736651, 2022). "The insulin homeostasis model is widely used to assess insulin resistance and insulin sensitivity." (PMID 36615858, 2022). "This hypothesis is strengthened by previous study that the hydroalcoholic extract could potentiates the action of insulin by reducing insulin resistance observed in type 2 diabetes or could activate translocation of GLUT4 glucose transporters." (PMID 36845227, 2022). "The elevation of HDL-c and PON-1, an enzyme that protects LDL from lipid peroxidation, was found after egg ingestions; therefore, individuals with metabolic syndrome who had consumed eggs presented a decrease in C-reactive protein levels, insulin levels, and insulin resistance, compared to baseline." (PMID 36313094, 2022). "Although statins have been considered a risk factor for insulin resistance in DM patients, pitavastatin did not significantly decrease insulin sensitivity, according to the results of no significant change of HOMA-IR and HOMAβ." (PMID 36431233, 2022). "In rats fed high fat diets, M. charantia freeze-dried unripe fruit juice (0.75%) could improve insulin resistance, as well as lower serum insulin and leptin." (PMID 35408574, 2022). "And the secretion of insulin from pancreatic β-cells and the insulin sensitivity of the peripheral target organs will decrease, which can induce the offspring to be insulin resistance, abnormal glucose and lipid metabolism, and overweight/obesity in the short- and long-term after birth." (PMID 36440470, 2022). "Glucose, insulin and insulin resistance (HOMA-IR) after 28 weeks." (PMID 35782914, 2022). "In cross-sectional studies, fasting pro-NT was associated with the presence of T2DM, both in non-obese and obese individuals, and correlated with indicators of poor glucose control and insulin resistance, such as higher glycosylated hemoglobin, fasting blood insulin, and HOMA-IR." (PMID 35216326, 2022). "The observed effects of the downregulation of circ_0001578 on proliferation, migration, and apoptosis in trophoblasts may explain chronic inflammation in the placenta, which can drive insulin resistance and lead to decreased insulin sensitivity." (PMID 36263320, 2022). "Moreover, clinical features associated with insulin resistance, such as the waist-to-hip ratio, SAT volume, serum insulin and C-peptide concentrations, and fasting plasma glucose concentrations, correlated inversely with THRSP expression." (PMID 35715726, 2022). "D. kaki fruit extract, gentiobiose, melibiose, and raffinose showed anti-insulin resistance and obesity-preventing effects by protecting β cells from high doses of human insulin induction, decreasing the abdominal size, and reducing the lipid accumulation in obese zebrafish." (PMID 36014755, 2022). "Insulin signaling in tissues sensitive to insulin is affected significantly by high levels of inflammatory cytokines and adipokines and aggravates hyperinsulinemia and insulin resistance." (PMID 36320802, 2022).
Insulin resistance (continued). "In addition, BCAA restriction in HFD helped maintain normal glucose and insulin levels and prevented insulin resistance." (PMID 36232982, 2022). "Importantly, the combination treatment reversed effects of rapamycin on markers of hepatic insulin resistance and normalized systemic insulin sensitivity in this inherently insulin‐resistant model." (PMID 35986566, 2022). "Furthermore, a study investigating the degree of salt intake’s effect on insulin resistance in hypertension-prone subjects suggested an interaction between salt intake, the renin-angiotensin-aldosterone system, and insulin action in men." (PMID 35566474, 2022). "On the other hand, the Lipoprotein Insulin Resistance Index (LP-IR)—a composite marker of six lipoprotein subclass and size parameters—appears to reflect adipose tissue insulin sensitivity, where the presence of high insulin levels impairs the suppression of lipolysis." (PMID 35834023, 2022). "Accompanied by decreased skeletal muscle mass, decreased insulin sensitivity, abnormal glucose, and fatty acid metabolism, the maintenance and increase of skeletal muscle mass may ameliorate insulin resistance." (PMID 35001531, 2022). "Herein, we found that ageing promoted insulin resistance and increased insulin secretion and that long-term hypercaloric diet intake exacerbates dysmetabolic states, characterized by insulin resistance, glucose intolerance, and increased insulin secretion, effects reversed by CSN denervation." (PMID 35600301, 2022). "Experimentally, ciclosporin may reversibly increase peripheral insulin resistance and decrease insulin secretion." (PMID 35448647, 2022). "One human positron emission tomography (PET) study with [18F]FDG found that middle-aged subjects with peripheral insulin resistance have blunted glucose metabolism response to insulin also in brain, especially in appetite-controlling regions such as ventral striatum." (PMID 34728775, 2022). "Moreover, a low HDL cholesterol level, due to hypercatabolism of HDL in the insulin-resistant state, is more common in patients with insulin resistance than hypertriglyceridemia is." (PMID 36079745, 2022). "In diabetic conditions, oxidative stress leads to insulin resistance, beta cell malfunction, and insulin secretion, all of which may be influenced by the phytochemicals with strong antioxidant properties." (PMID 36558046, 2022). "The possible mechanism by which insulin modulates Lp(a) synthesis may be that increased insulin levels promote the progression of insulin resistance and, under these circumstances, reduce the synthesis of Lp(a)." (PMID 35528012, 2022). "Uric acid can also inhibit insulin signaling and induce insulin resistance." (PMID 35656391, 2022). "Insulin resistance (IR) occurs when more insulin is required to achieve the same effects, and IR may be tissue-specific." (PMID 35991189, 2022). "Moreover, they have found an impairment in the central regulation of peripheral insulin signaling in obese people, showing the tight link between brain and peripheral insulin resistance in dysmetabolism conditions." (PMID 35406040, 2022). "In light of the marked inter-ethnic variation in the contribution of insulin secretion and insulin resistance, questions have been raised on whether reduced GLP-1 secretory response represents a universal characteristic of T2DM patients." (PMID 36157456, 2022). "Insulin resistance (IR) is a complex metabolic disorder characterized by the attenuated responsiveness of peripheral tissues, primarily muscle, liver, and adipose tissue, to insulin signaling, so insulin release is increased to maintain glucose homeostasis." (PMID 36002887, 2022). "It is plausible that the increased insulin sensitivity conferred by alcohol consumption could offset adiposity-induced insulin resistance in both women and overweight populations." (PMID 35901054, 2022).
Insulin resistance (continued). "Moreover, the overexpression of RBP4 or recombinant RBP4 injection induces insulin resistance, whereas RBP4 deficiency increases insulin sensitivity." (PMID 35909571, 2022). "Among those with DM and CVDs, low blood levels of chromium are prevalent and this might be due to the diminution of insulin signal transduction and contribute to insulin resistance." (PMID 35807870, 2022). "Importantly, abrogation of the GSK3β-mediated ERRα phosphorylation at S19, S22 and S26 in vivo led to altered insulin-dependent liver and muscle transcriptomes, compromised metabolism and insulin resistance." (PMID 35440636, 2022). "DM can be classified into three major types: type I DM (insulin-dependent) due to immune-mediated β cells destructions; type II DM (non-insulin-dependent) due to an insulin secretory defect and insulin resistance as well as gestational diabetes that develops during pregnancy." (PMID 36380337, 2022). "HENS treatment had improved effects on the HOMA indexes, which could be due to reduced insulin resistance in peripheral tissues, increased insulin secretion from the pancreas, or repair of damaged β-cells." (PMID 36109786, 2022). "A study using leukocytes from obese humans looked at the molecular mechanisms of insulin resistance; specifically, they set out to determine whether changes in the mtDNA may explain the mitochondrial abnormalities of insulin-resistant obese patients." (PMID 36093112, 2022). "The main finding of this study is that the SPISE index correlates with insulin-derived indicators of insulin resistance and sensitivity in children, and significantly predicts the development of glucose metabolism abnormalities later in life in this population." (PMID 34142364, 2022). "In addition to hyperglycemia, emerging evidence implies that insulin resistance in the brains of PD patients and impaired brain insulin signaling are potential contributors to PD pathogenesis." (PMID 35761385, 2022). "Insulin resistance and impaired insulin secretion remain to be two major characteristics of T2DM." (PMID 36246870, 2022). "Resistin is considered an important pro-inflammatory mediator and may play a role in the instauration insulin resistance through actions antagonistic to those of insulin." (PMID 35624765, 2022). "The prominent characteristic of T2DM is insulin resistance, which impairs the action of insulin." (PMID 35414044, 2022). "Indeed, insulin levels are elevated in insulin resistance because the β-cells have to compensate for the decreased peripheral insulin sensitivity." (PMID 35659558, 2022). "Some articles reported DPP4i improves insulin secretion and insulin resistance." (PMID 35672759, 2022). "In addition, long sleep duration shows some detrimental influence on insulin resistance and insulin sensitivity." (PMID 36277903, 2022). "TET2 has been suggested to facilitate the transcriptional activity of peroxisome proliferator-activated receptor gamma (PPARƴ), involved in insulin sensitivity; thus, a TET2 loss-of-function may have promoted insulin resistance." (PMID 36009574, 2022). "Additionally, the glycogen levels are lower in diabetic individuals, which most likely are due to insulin resistance and a reduced insulin production." (PMID 36094958, 2022). "Lipid accumulation, liver histopathology, insulin resistance, and core gene expression were measured by oil red O staining, hematoxylin and eosin staining, insulin tolerance test, real-time quantitative polymerase chain reaction, and Western blotting, respectively." (PMID 36506575, 2022). "The probable mechanism by which both ACE and electro-acupuncture have positive effects in reducing weight in obese patients may be related to its effects in downregulating serum leptin and insulin levels and correcting leptin resistance and insulin resistance." (PMID 35265146, 2022).
Insulin resistance (continued). "FCGR is a measure of the amount of insulin secreted for a corresponding glucose level, and is considered a simplified index in the evaluation of insulin resistance compared with the euglycemic hyperinsulinemic clamp, which was regarded as the previous “gold standard”." (PMID 35757395, 2022). "It was believed to induce insulin resistance in adipose tissues by altering the normal insulin signaling pathway, stimulating adipocyte lipolysis, inhibiting serine phosphorylation of IRS-1 activity thereby decreasing glucose transporter ‘GLUT4’ synthesis and membrane translocation." (PMID 36434695, 2022). "In our study, we could not establish such a correlation between OPG levels and indexes of insulin sensitivity and insulin resistance." (PMID 36578961, 2022). "Indeed, in a physiological state, insulin suppresses lipolysis in adipose tissue, but through adaptive insulin resistance HGF/VEGF expression can decrease the suppressive action of insulin on lipolysis and thus increase fatty acid plasma concentration." (PMID 36497083, 2022). "However, recent studies have observed that some patients show insulin hypersecretion before the development of glucose intolerance, suggesting that hyperinsulinemia can occur before insulin resistance." (PMID 35448552, 2022). "It is based on complex disorders of insulin secretion and insulin resistance." (PMID 35893051, 2022). "This crossroad of insulin signaling and transcriptional control by a nuclear receptor offers a framework to better understand the complex cellular processes contributing to the development of insulin resistance." (PMID 35440636, 2022). "This reveals a protective role of INK4A/ARF locus against age-induced insulin resistance, whereas increased insulin secretion, attenuated insulin sensitivity, and reduced hepatic insulin clearance were observed upon loss of function mutation of the Cdkn2a gene." (PMID 36143369, 2022). "The serum levels of ferritin and insulin were significantly higher in group A than the group B. Similarly, the serum insulin resistance calculated based on the formula was found to be significantly higher in group A (5.91 ± 1.21) than in group B (3.55 ± 1.17) with p < 0.001." (PMID 35893594, 2022). "Our results showed that insulin resistance, rather than insulin therapy, increases the risk of severe CAD in T2DM patients with inadequate glycemic control." (PMID 36238131, 2022). "Therefore, excessive nutrients, such as glucose and fatty acids, lead to an abnormal increase in global O-GlcNAcylation, which reduces insulin signal transduction efficiency, produces insulin resistance and forms a vicious circle and glucose toxicity." (PMID 35681484, 2022). "Specifically, evidence of AP-induced brain insulin resistance may advise use of adjunctive treatment with targeted central insulin sensitizers to address metabolic and possibly cognitive dysfunction at the earliest stages of the illness." (PMID 36441736, 2022). "Moreover, IRW and IQW increased glucose tolerance and insulin resistance based on the results of the intraperitoneal glucose test and insulin tolerance test (p < 0.05, n = 8)." (PMID 36232527, 2022). "Since insulin levels were elevated at puberty, and insulin receptor signaling is necessary for β cell compensation to insulin resistance, we asked whether insulin might mediate the increase in β cell proliferation in response to pubertal serum." (PMID 36107617, 2022). "The reason may be described that in NAFLD mice, insulin resistance is distinct, and the effect of insulin to inhibit lipolysis of adipose tissue is weakened, which leads to increased delivery of free fatty acids to the hepatocytes." (PMID 35907871, 2022). "A 2012 meta-analysis of 16 studies, which included 46,236 participants, demonstrated that pooled relative risk of CVD per 1-SD increase was 1.13 (95% CI: 1.05, 1.22; I2:58.3%) for insulin and 1.25 (95% CI: 1.16, 1.35; I2:52.4%) for Homeostatic Model Assessment for Insulin Resistance (HOMA-IR)." (PMID 36386371, 2022).